IL6 (interleukin 6)
Diseases named in the same sentence as IL6 in open-access papers (continued):
Sharing a sentence is not in itself a finding about the gene and the disease.
Arthritis (continued). "Similarly, a previous study demonstrated that IL-6 knockout mice were only mildly protected from mBSA/IL-1β-induced arthritis." (PMID 28587618, 2017). "Supporting the anti-inflammatory role of PRL in arthritis, PRL-receptor-null mice exhibited increased joint swelling and higher joint expression of the genes encoding for TNFα, IL-1β, IL-6, IFNγ, IL-17A, IL-21, IL-22, IL-23, and IL-10 when subjected to monoarticular AIA (MAIA)." (PMID 28506283, 2017). "Overall, this study confirmed the importance of IL-6 and IL-21 during Th17 development in vivo, and showed higher potency of blocking both cytokine pathways above blocking either one in reducing the severity of arthritis." (PMID 28158305, 2017). "In fact, IL-6 was consistently expressed at very low levels by Zfp36aa/aa mice following systemic LPS challenge, the injection of zymosan into dorsal air pouches, or the induction of experimental arthritis." (PMID 28265004, 2017). "IL-6 is one of the cytokines that promotes the development of arthritis." (PMID 29212197, 2017). "The aim of this study was to assess whether combinatorial IL-6/IL-21 blockade would more potently inhibit Th17 development, and be more efficacious in treating arthritis than targeting either cytokine." (PMID 28158305, 2017). "Additionally, anti-IL-6/anti-IL-21 treatment of CIA mice during the arthritis induction phase reduced disease development more potent than IL-6 or IL-21 inhibition alone, as effective as anti-TNF treatment." (PMID 28158305, 2017). "In the inflammatory state, IL-6 is an important proinflammatory cytokine that can promote the differentiation of naive T cells into Th17 cells, suppress the differentiation of Treg cells, and accelerate the progression of experimental arthritis." (PMID 26841872, 2016). "The inhibitory effects of neovestitol on IL-6 release in the joints of mice with arthritis may be related to the increased levels of nitric oxide (iNOS pathway), as observed in the acute inflammation assays." (PMID 27819273, 2016). "Although the presence of arthritis in ApoE−/− mice was associated with increased levels of G-CSF, KC/Gro-a and decreased levels of IL-21, IL-23 and MIP-2, the greatest change was observed in IL-6." (PMID 27287704, 2016). "IL6 is a well-known soluble mediator of inflammation involved in the pathogenesis of arthritis and is currently a target for treatment in both children and adults with arthritis." (PMID 27244050, 2016). "Furthermore, the action of IL-6 in the collagen-induced arthritis model was demonstrated to be related to Th17 differentiation." (PMID 27819273, 2016). "Our results also showed enhanced migration capacity of TIARP−/− neutrophils, which was mediated mainly through CXCL2, and that IL-6 signaling is critical for the recruitment of neutrophils into the arthritic joints after serum-transferred arthritis in TIARP−/− mice." (PMID 27995997, 2016). "In this study, we first confirmed the therapeutic effects of MSCs on CIA mice, using generally applied quantification methods, including the paw thickness, clinical arthritis score, histological arthritis score, and modulation of proinflammatory cytokines, like IL-1β, IL-6, TNF-α, IL-10 and TGFβ1." (PMID 27354158, 2016). "Moreover, neovestitol inhibited the development of collagen-induced arthritis per modulation of IL-6 release." (PMID 27819273, 2016). "IL-6 plays role in arthritis but its role in SpA pathogenesis is controversial." (PMID 28053373, 2016). "In addition, administration of IL-6 receptor neutralising antibodies at the time of CIA induction completely abolished the inflammatory response indicating that IL-6 plays an important role in the initiation of arthritis." (PMID 26634933, 2016). "Deficiency of either IL-6 or IL-17 completely inhibits the arthritis, whereas lack of IFN-γ can exacerbate disease in SPF mice." (PMID 27288531, 2016).
Arthritis (continued). "The differential contribution of the classical and trans-signaling IL-6 pathways in cell-mediated inflammatory processes was recently demonstrated in the experiment of pharmaceutically targeting each of them using two murine models of human arthritis." (PMID 26403459, 2016). "Therefore, there is a possibility that the decreased activation of the IL-6-Th17 axis, a direct arthritogenic cascade, reduced the severity of arthritis in the GIA models." (PMID 26293116, 2015). "IL-6 signaling in sensory neurons plays a role in the expression of arthritis." (PMID 26590032, 2015). "This study explored whether the action of IL-6 on sensory neurons plays a role in the generation of neurogenic inflammation and arthritis induction." (PMID 26590032, 2015). "However, an unpredictable flare-up of arthritis of all joints and highly elevated IL-6 circulation was observed." (PMID 26186692, 2015). "Effect of different variables on IL-6 serum levels in patients with early arthritis." (PMID 26569609, 2015). "Considering the inhibitory potential of these cytokines on many proinflammatory mediators like IL-17, IL-6 and IL-1β, they may contribute to the observed suppression of arthritis severity." (PMID 26110994, 2015). "NF-κB is a transcription factor that acts as a significant part on the onset of inflammation by modulating the expression of pro-inflammatory cytokine (TNF-α, IL-1β, IL-6 and IL-17) genes involved in immune responses, which are all closely connected with the pathogenesis of arthritis." (PMID 26709520, 2015). "Here, we demonstrated that a single treatment with FBP markedly attenuated arthritis, assessed by reduction of articular hyperalgesia, joint swelling, neutrophil infiltration and production of inflammatory cytokines, TNF and IL-6, while enhancing IL-10 production in two mouse models of arthritis." (PMID 26478088, 2015). "IL-6 has also been proposed to contribute to the development of arthritis." (PMID 24511322, 2014). "IL-6 is a key player in systemic inflammation and arthritis." (PMID 25606597, 2014). "This is in contrast to arthritis-susceptible B6 IL10−/− mice, where previously published data show that in addition to upregulation in IL-1β, IL-6, Cxcl1 and Cxcl2, IFNγ and Cxcl10 are upregulated 16-fold and 141-fold at 2 weeks, and 22-fold and 189-fold at 4 weeks, respectively." (PMID 24967703, 2014). "Indeed, IL-6 has a role in the differentiation of B lymphocyte into auto-antibody producing plasma cells, which participate in the pathogenesis of arthritis through the formation of immune complexes (IC)." (PMID 25271853, 2014). "Furthermore, IL-6 inhibition increases the frequency of functionally suppressive Tregs in both experimental and human arthritis." (PMID 24877127, 2014). "Earlier study described CCN1 regulating IL-6 expression during arthritis process." (PMID 25187949, 2014). "However, in our previous study, the resulting effect of dendrimer ABP action in arthritic mice was a dramatic decrease of both IL-1β and IL-6, suggesting a strong in vivo capability to decrease inflammatory cytokines involved in arthritis." (PMID 24745366, 2014). "IL-6 has significant implications in the development of arthritis." (PMID 25561237, 2014). "Overexpression of MARCH8 in DCs of a CII-induced arthritis mouse model leads to reduced arthritis as well as TNFα and IL6 expression in synovial tissues, indicating that expression of MARCH8 alters the local inflammatory immune response but not the systemic immune response." (PMID 27419207, 2014). "Similarly, in a rodent model of arthritis, IL-6 contributes to inflammatory pain, neuronal hyperexcitability and increased neuronal CGRP levels." (PMID 24650225, 2014). "Indeed in our previous publications, we have shown that BC-associated metastasis is significantly augmented in mice with arthritis and that IL-17A, IL-6, COX-2, VEGF, MMP-9, IGF-II, M-CSF and TNF-α are all major players." (PMID 24674692, 2014).
Arthritis (continued). "More recently, evidence has also been obtained demonstrating that the anti-inflammatory effect of Ebosin on rat collagen-induced arthritis is through suppressing production of interleukin-1β, interleukin-6 and tumor necrosis factor α at both transcriptional and posttranslational levels." (PMID 25048214, 2014). "In addition, blocking S100A9 resulted in diminished TNFα and IL-6 expression in a collagen-induced arthritis model." (PMID 23977231, 2013). "However, after induction of arthritis, we observed the local up-regulation of pro-inflammatory IL-6 and MMP-3 in both HO-1+/− and HO-1−/− animals with respect to wild type mice." (PMID 23285041, 2012). "Taking into account that this adipokine has been shown to be downregulated by cytokines such as TNF and IL6, arthritis-induced decrease in adiponectin may be due to the inflammatory mediators." (PMID 23781298, 2012). "In this model, the deficiency of TNF, but not IL-6, suppressed the development of arthritis and skin inflammation." (PMID 23133751, 2012). "IL-6 levels had returned to baseline levels by day 4 after arthritis induction." (PMID 22676339, 2012). "Unlike the CIA model, the CAIA model has been shown not to be entirely dependent on IL-6, as arthritis can still be induced in mice deficient in this cytokine." (PMID 21510883, 2011). "The present results suggest that the use of sgp130 as an inhibitor of the IL-6 pathway in an array of inflammatory conditions, from arthritis to neuroinflammatory disorders, may mitigate IL-6 expression and have a beneficial effect on behavioral responses." (PMID 21595956, 2011). "Increased serum IL-6 in arthritis is a marker of the general inflammatory disease." (PMID 21159208, 2010). "The aim of the present study was to better understand the mechanisms underlying the suppressive effect of MSCs in vivo, using cells isolated from mice deficient in the production of inducible nitric oxide synthase (iNOS) or interleukin (IL)-6 in the murine model of collagen-induced arthritis." (PMID 21151872, 2010). "For example, IL-6 and IL-23 stimulate T-cells for induction of Th17 immune responses, which are operant in autoimmune diseases such as inflammatory bowel disease, lupus, psoriasis and arthritis." (PMID 21067617, 2010). "In addition to its pathogenetic role in chronic inflammation and bone destruction, IL-6 in the joint plays a significant role in the generation and maintenance of arthritic joint pain at acute and chronic stages of arthritis." (PMID 20626857, 2010). "In contrast to wild type MSCs, IL-6-deficient MSCs and to a lesser extent iNOS-deficient MSCs were not able to reduce the clinical signs of arthritis." (PMID 21151872, 2010). "However, deletion of IL-6 gene has resulted in protection from the induction of collagen-induced arthritis or a reduction in the disease parameters." (PMID 19368720, 2009). "Intra-articular administration of IL-6 into the joints of IL-6-deficient mice did not lead to arthritis, but a soluble IL-6/IL-6R fusion protein caused joint swelling and other symptoms of arthritis." (PMID 19368720, 2009). "Overall, arthritis was less severe in animals treated with IL-6 antibody." (PMID 19368720, 2009). "In the next step, we assessed the effect of IL-6 blockade in mice with GPI-induced arthritis." (PMID 18534002, 2008). "Inhibition of TNFα, IL-1β, and IL-6 production is beneficial in several inflammatory diseases including arthritis and numerous efforts have been devoted in the design of novel therapies aimed at blocking the production and/or the biological effects of these important pro-inflammatory cytokines." (PMID 18493620, 2008). "Surprisingly, a single injection of anti-IL-6 mAb resulted in cure of arthritis." (PMID 18534002, 2008). "Therefore, the effectiveness by IL-6 antagonist on day 8 in GPI-induced arthritis appears to be mediated through orchestration of these mechanisms." (PMID 18534002, 2008).
Arthritis (continued). "With regard to cytokine dependency, anti-TNF-α mAb does not prevent the development of arthritis in K/B × N mice, and IL-6 deficiency has no influence on the development of arthritis by K/B × N serum transfer." (PMID 18534002, 2008). "IL-6 and leukemia inhibitory factor, which both belong to the same family of cytokines, are known to participate substantively in the pathogenesis of murine models of arthritis as well as RA." (PMID 15642131, 2005). "Elevated expression of IL-6 and TNF-α in pericytes and smooth muscle cells indicates their involvement in inflammatory signaling and tissue remodeling within adipose stromal tissues, which may contribute to arthritis-associated inflammation." (PMID 40266392, 2025). "Moreover, studies involving LPS-induced macrophages and adjuvant-induced arthritis in rats demonstrate that the production of pro-inflammatory cytokines such as IL-6, IL-1β, and TNF-α requires activation through the NF-κB, JAK1-STAT1/3, and MAPK signaling pathways to exert inflammatory effects." (PMID 40170729, 2025). "The addition of IL-27 into IL-23-induced arthritis mice ameliorated disease incidence and disease severity, inhibited neutrophil proliferation and γδ T-cell accumulation, and resulted in reduction in serum levels of IL-6, IL-17, and IgG2a, and percentage of cells expressing IL-17 and IFNγ." (PMID 38566992, 2024). "It is worth mentioning that the highly concerned oral bacteria, Porphyromonas gingivalis, could also cause intestinal flora dysbiosis, improve the Th17 cell proportions in mesenteric lymphocytes and the level of citrullinated protein and IL-6, and then aggravate arthritis." (PMID 36936921, 2023). "Furthermore, the relevance of the feedback between TNF-α and S100-proteins has been confirmed for inflammatory processes like arthritis and psoriasis and IL-6 is the top cytokine induced by S100A8/S100A9 in myeloid cells as shown in a genome wide transcriptome analysis." (PMID 37056775, 2023). "Therefore, tofacitinib seems to have profound suppressive effect on IL-6 production in arthritis." (PMID 36124688, 2022). "However, other studies provide evidence pointing towards the fact that IL-6 blockade would be more useful for the arthritis component of the disease, and still others suggest that the efficacy of IL-1 blockade would be limited to the systemic features of the disease." (PMID 33892792, 2021). "However, the relationship between IL-6 and neutrophils in arthritis remains obscure." (PMID 34299252, 2021). "The progression of arthritis disease is regulated by several microRNAs (miRNAs), including miR-92a, miR-129-3p, miR-141-3p and miR-199a-5p, while the proinflammatory mediators IL-1β, IL-6, TNF-α and matrix metalloproteinases (MMPs) account for histological changes that occur with arthritis." (PMID 34198264, 2021). "However, the occurrence of skin rash, arthritis, sore throat, lymphadenopathy, hepatosplenomegaly, leukocytosis, disease activity scores, and levels of ferritin, IL-1, IL-6, IL-17A, IL-18, TNF-α, LC3-II mRNA, or ATG16L mRNA expression was not predictive of the systemic pattern." (PMID 34208077, 2021). "Indeed, blockade of CDH11 attenuates inflammation in mouse models of arthritis, an effect that may be due in part to reduced IL-6 production by CDH11+ synovial fibroblasts." (PMID 31156640, 2019). "In arthritis, proliferative fibroblast-like synoviocytes (FLSs) play key roles in joint damage and in the propagation of inflammation because they produce considerable amounts of proinflammatory mediators, such as interleukin-6 (IL-6) and prostaglandin E2 (PGE2)." (PMID 30565030, 2019). "In previous scientific publications, high levels of IL-6 have been reported in adult patients with symptomatic meniscal tears, suggesting IL-6 could be involved in pain generation; IL-6 is also involved in the cartilage catabolic process and arthritis development." (PMID 30245587, 2018).
Arthritis (continued). "Therefore, we used IL-6 plus sIL-6R administration in the right knee to induce arthritis in rats." (PMID 29867478, 2018). "Furthermore, it proposes for consideration/reconsideration the assessment of IL-6 and other markers of arthritis including systemic autoantibodies and, as proposed previously, C-reactive protein for monitoring the disease and therapy response in ovarian cancer." (PMID 27527602, 2016). "Furthermore, pro-inflammatory cytokines such as Il6 and Il1β were increased at mRNA and protein levels in ΔdblGATA arthritic mice compared with WT controls, suggesting that eosinophils play an important role in determining the severity of arthritis." (PMID 27273006, 2016). "In addition, other studies have reported lower circulating levels of IL-6 in CC homozygous patients with different types of cancer, arthritis, cirrhosis, pancreatitis, retinal idiopathic Eales’s vasculitis, surgical coronary revascularization and end-stage renal disease on hemodialysis." (PMID 27834822, 2016). "However, whether ciclamilast can inhibit IL-1β and IL-6 and protect against arthritis remained unknown." (PMID 26000303, 2015). "Overall, these results demonstrate that high levels of IL-6/sIL-6R, as those present in joints of patients with arthritis, may contribute to the amplification of the inflammatory response enhancing the production of IL-1β, CXCL8 and CCL2 by SFMCs and by RA synoviocytes." (PMID 25271853, 2014). "Moreover it has been suggested that IL6 can act as a peripheral pain mediator in a model of arthritis; indicating that it could have the same role in UVB treated skin." (PMID 24732968, 2014). "Thus, IL-23 may have other affects on the development of arthritis such as the induction of IL-1β and IL-6." (PMID 25253467, 2014). "Interestingly, other proinflammatory cytokines participating in arthritis, including IL-6, have been reported to activate cathepsin B and therefore could also trigger the cleavage of Sirt1." (PMID 23844973, 2013). "Another member of the tenascin family, Tenascin C (Tnc), was recently shown to be an endogenous activator of TLR4, an inducer of IL-6 and TNFα, and was required for joint damage in arthritic mice, suggesting that Tnn could have a function similar to Tnc in arthritis." (PMID 23249408, 2012). "Interestingly, IL-6 was required for IL-17A-induced arthritis, in Y759F mutants." (PMID 22229105, 2012). "Evidence from clinical studies shows that earlier in the disease, IL-1 inhibitors (and perhaps also IL-6 blockade) are efficacious, especially against systemic symptoms, but at a later stage, where arthritis may predominate, patients may develop resistance to these therapies." (PMID 23092393, 2012). "Furthermore, studies suggesting an involvement of IL-6 in the induction of Th17 cells in arthritis models have been reported: anti-IL-6R antibody suppressed the onset of arthritis in G6PI-induced and collagen-induced arthritis models and concomitantly inhibited the appearance of Th17 cells." (PMID 22046525, 2011). "Arthritis index (AI), joint histology, serum cytokines (TNF-α, IL-6, IL-17, and TGF-β), and metabolites (lactate and pyruvate) were assessed." (PMID 42260739, 2026). "In an adjuvant-induced model of arthritis (AIA), significant increases in cytokines (including IL-1, IL-6 in the pituitary gland and spleen, IL-6, and IL-1β) have been found after the adrenal glands of the animals have been removed." (PMID 41229441, 2025). "Along these lines, the P2X4 receptor antisense oligonucleotides reduced synovial inflammation in the collagen-induced mouse model of arthritis by modulating the serum levels of IL-1β, TNF-α, IL-6, and IL-17." (PMID 41002432, 2025). "These targets modulate the IL-6/STAT1/STAT3 pathway, which has been shown to significantly prevent and treat gout and arthritis." (PMID 40170729, 2025).